MUC1 (mucin 1, cell surface associated)
Diseases named in the same sentence as MUC1 in open-access papers (continued):
Sharing a sentence is not in itself a finding about the gene and the disease.
tumor (continued). "In multiple studies, GO-203 exhibited dose-dependent activity against MUC1-expressing human tumor xenograft models." (PMID 35897789, 2022). "In patient-derived xenograft (PDX) model, anti-MUC1 CAR-T cells were unable to effectively slow down the development of an NSCLC tumor mass." (PMID 36423060, 2022). "The expression of F3 and MUC1 proteins using the HPA database showed increased (high or medium) immunostaining intensity in PCa tumor tissues; however, the expression remained low or undetectable in normal prostate tissues." (PMID 36012492, 2022). "MUC1 is a transmembrane glycoprotein, which is attention due to its unnormal expression in tumor tissues (people patients) for detection." (PMID 36091438, 2022). "Although the MUC1-Vax vaccine has shown considerable prospects in anti-tumor therapy, we are aware of some limitations of this study." (PMID 35891256, 2022). "Tumor cell-expressed MUC1 is another line, and it has a certain effect on immunocyte function and phenotypes within the tumor microenvironment (TME)." (PMID 35883508, 2022). "MUC1 has substantially altered roles within cancer tissues, which is closely related to tumor development and treatment." (PMID 35883508, 2022). "The sera from the TF-conjugated glycopeptides recognized multiple MUC1 isoforms, weas cytotoxic to MUC1-bearing tumor cells and protected mice from tumor challenge post vaccination." (PMID 35432351, 2022). "The findings illustrated that the mRNA expression level of MUC1 changed significantly across various tumour stages in LUSC, being higher at stages I and IV than at stages II and III." (PMID 36059804, 2022). "Analysis of scRNA-seq TNBC data further supported the significant association between MUC1 and expression of IRDS genes encoding IRF7, BST2, IFI35 and IFITM1 in individual TNBC tumor cells." (PMID 35681561, 2022). "MUC1 can contribute to different tumor invasions and migrations by regulating tumor cell invasion and metastasis-related factors." (PMID 35883508, 2022). "Conversely, the presentation of an MUC1 epitope was reduced after transfection of tapasin in the Pan02-MUC1 tumor cell line." (PMID 36389776, 2022). "MUC1 represents a critical tumor marker that is highly expressed within BRCAs, so it has become a possible antibody-based therapeutic target." (PMID 35883508, 2022). "In this case, the clear tumor cells showed positivity of MUC-1, cytokeratin 7, and cytokeratin 19, and showed negativity of vimentin and neuroendocrine markers, which indicate pancreatic clear cell carcinoma with ductal phenotype." (PMID 36140448, 2022). "We report here a first-in-human, phase 1 study of Ad-sig-hMUC1/ecdCD40L therapeutic cancer vaccine directed against the MUC1 tumour antigen." (PMID 36307410, 2022). "As expected, compared to ppM1 alone treatment, both therapies of ppM1 in combination with either PD-1 antibody or MUC1 vaccine demonstrated further improved outcomes in the decreased tumor volumes and in the extended mouse life span." (PMID 35712073, 2022). "Compared to normal tissues, the expression levels and glycosylation patterns of MUC1 are highly dissimilar in tumor tissues." (PMID 36499455, 2022). "As suggested in one work, a tumor-bearing MUC1 damaged DC activity and differentiation by upregulating CD1a/CD206, two factors related to the immature phenotype of DCs." (PMID 35883508, 2022). "Increased expression of known EAC-associated genes such as MUC1 and AGR2 was observed within the tumour." (PMID 36253784, 2022). "In support of the importance of B cell function, we found upregulation of Th2 immune genes and complement genes shared between IP fluid and tumor tissue and are the first to report the presence of anti-MUC1 antibodies in IP fluid." (PMID 36428740, 2022). "To date, four tumor vaccines targeting MUC1 have entered clinical trials: MUC1 peptide vaccine, antiMUC1 monoclonal antibody vaccine, MUC1-specific immune cell vaccine, and MUC1-expressing recombinant viral vector vaccine." (PMID 36142800, 2022).
tumor (continued). "The microenvironmental anti-inflammatory properties of bromelain by uncoated cancer cells (depolymerizing MUC-1, fibrin and albumin) through increasing adhesion of lymphocytes to the tumor are thought to expose the tumor to host defense." (PMID 36506883, 2022). "A protein coupled with MUC1 antibody and Fc receptor was developed, which was highly specific to tumors, and applied to tumor immunotherapy." (PMID 36072925, 2022). "The activities of CA1, ANXA10, and MUC1 were increased in LPS treated IBD enteroids compared to the LPS treated tumor enteroids, while the activities of BAAT, ACSL5, and ENPP6 were decreased." (PMID 35884586, 2022). "According to their results, the dual targeting of CARs promoted the growth of CAR T-cells while effectively killing tumor cells co-expressing MUC1 and ErbB2." (PMID 35883508, 2022). "SZU251 + MUC1 + Al showed the best prophylactic effects with suppression of the tumor growth and extension of the survival time of the mice." (PMID 36499455, 2022). "Recently, poly(lactic acid)-PEG-Apt/Dox NPs have also developed as a tumor-targeting delivery system based on MUC1 aptamer-targeted nanoparticles for anticancer activity on the MUC1-overexpressing A-549 cell line (human alveolar basal epithelial cells)." (PMID 36559325, 2022). "In present study, we reported a facile synthesis method of a nanobody against tandem repeats of MUC1 and investigated its tumor suppressive, anti‐angiogenic, and anti‐metastatic effects in vivo and in vitro." (PMID 34694686, 2022). "In 2011, the study was further extended to open-label randomized trial III, which comprised 100 and 48 patients expressing MUC1 in their tumor with stage IIIB and stage IV NSCLC, respectively." (PMID 36423060, 2022). "The interaction of MUC1 and galectin-3 promotes cancer spread by altering tumor cell surface polarization and increasing the exposure of cell surface adhesion molecules." (PMID 36497322, 2022). "In 2012, a significant correlation was found between the MUC-1 expression level and the histopathological grade of tumor malignancy in human studies." (PMID 35000604, 2022). "There is a different expression pattern of MUC-1 in both human and canine breast tissues, as well as in normal breast epithelial and tumor cells." (PMID 35000604, 2022). "Recent studies have found that MUC1 plays an important role in tumor hypoxia microenvironment and tumor metabolism." (PMID 35879749, 2022). "On the other hand, MUC1 also results in chemoresistance and radio-resistance during cancer therapy; a third pathway is MUC1-promoting tumor invasion and migration." (PMID 35883508, 2022). "This category includes overexpressed antigens such as HER2 and mucin-1 (MUC-1), tissue differentiation antigens such as carcino-embryonic antigen (CEA), and tumor germline antigens like melanoma-associated antigen." (PMID 35154149, 2022). "The as-constructed vaccine triggered outstanding IgG antibody titers and potently combined with BRCA cells that expressed tumor-related MUC1." (PMID 35883508, 2022). "The MUC1 aptamer was coupled to the nanoparticle surface and enhanced the selectivity of miRNA-29b for tumor cells and tissues." (PMID 36072925, 2022). "Especially in Panc02-bearing-mice immunized twice with MUC1-Vax DCs, showed significant tumor shrinkage, while tumors in PBS-DCs and PDL1-DCs groups shrank only slightly or not at all." (PMID 35891256, 2022). "After exposure, the APDTRP epitope with abnormally glycosylated MUC1 is identified via several antibodies against MUC1, thus activating cytotoxic T-lymphocytes (CTLs) specific to tumor antigens." (PMID 35883508, 2022). "The cytoplasmic tail of MUC1 (MUC1-CT) is involved in many signaling cascades including those involved in tumor cell resistant-development, proliferation, and survival, as well as cell-cell and cell-matrix interactions." (PMID 33836774, 2021).
tumor (continued). "Biodistribution in SCID mice bearing MCF7 xenografts, demonstrated excellent tumor uptake (12% ID/g) and favorable kinetics for MUC1-FA-[18F] SFB over MUC1-[18F]SFB." (PMID 33738611, 2021). "In support of these results and importantly, analysis of the TCGA and SU2C PC tumor datasets demonstrated that MUC1 significantly correlates with activation of the NFE2L2.V2 signature and SLC7A11 and G6PD gene expression." (PMID 34163028, 2021). "Confirming previous analyses, MUC1 expression was detectable in TNBC tumor cell populations, along with STAT1 and IRF1." (PMID 33495298, 2021). "Western blot analysis of tumor tissues showed that MUC1 overexpression partially rescued the effect of YBX1 silencing on CD133, Oct-4, MMP9, E-cadherin, β-catenin, and Snail expression." (PMID 34976785, 2021). "In addition, MUC1 has been associated with immune checkpoint genes, neoantigens, and certain prognostic indicators of immunotherapy such as tumor mutational burden (TMB) and microsatellite instability (MSI), suggesting that it may also serve as a target and prognostic biomarker for immunotherapy." (PMID 34207342, 2021). "The MUC1 will be then differentiated through the process of glycosylation and over expression on tumor cells signifying the importance of this protein in the maintenance of the tumor and its progression." (PMID 33670011, 2021). "In summary, these newly generated humanized anti-MUC1 antibodies importantly enhance NK cell-mediated cytotoxicity against different MUC1-Tn/STn epitope-positive tumor cells." (PMID 34070311, 2021). "CTL activity and tumor growth inhibition was significantly enhanced in vivo in mice vaccinated with a combination of MUC1 and BIRC5 tumor gene vaccine." (PMID 33431968, 2021). "Ectopically expressed MUC1 in rat fibroblasts induces their cellular transformation and tumor formation in the mouse." (PMID 34681277, 2021). "Thus, in addition to its influence on promoting tumour cell spreading by interaction with tumour cell-associated MUC1 as reported in our earlier study, circulating PNA could also influence metastasis by enhancing the secretion of metastasis-promoting MCP-1 and IL-6 from the endothelium." (PMID 34223877, 2021). "Disruption of the cell-cell and cell-matrix adhesions, due to MUC1 overexpression by the tumor cells, is believed to play a role in invasive cancer growth and metastasis." (PMID 34445181, 2021). "As a pro-inflammatory agent, MUC1 promotes inflammation through different pathways by modulating related biomolecules in the tumor microenvironment and during EMT, and through altered glycosylation, contributing to the further progression to tumor formation." (PMID 34207342, 2021). "Further investigation on circulating MUC1 for the chemotaxis of T cells in the tumor microenvironment would be interesting and the intensive molecular mechanisms are worthy of more elaborate study." (PMID 33718143, 2021). "All previous studies have reported the role of MUC1 expressed in the tumor microenvironment on MDSC recruitment and function." (PMID 34070449, 2021). "In one study (NCT03114631), DCs generated from blood monocytes and pulsed with tumor lysates or tumor antigens MUC1 and WT1 were injected subcutaneously to 26 patients with stage II–IV pancreatic cancer." (PMID 34290984, 2021). "New radiolabeled conjugates and peptides with desirable biological properties have also been used to target tumor-specific MUC1 antigens to diagnose and treat cancers." (PMID 34207342, 2021). "For instance, MCF-7 circulating tumor cells were detected by an electrochemical cytosensor with effective surface recognition between specific mucin 1 protein (MUC-1) over-expressed on the MCF-7 cell membranes and MUC-1 aptamer." (PMID 33468160, 2021).
tumor (continued). "Instead, the addition of extra NK cells (higher E:T ratios) was the main determinant of tumor cell killing: in the presence of anti-MUC1 antibodies, the average tumor kill increased with on average 12.8% with every doubling of the E:T ratio." (PMID 34070311, 2021). "The percentage of MUC1-positive tumor cells by immunohistochemistry (IHC) and the staining intensity were evaluated by two observers blinded to outcome." (PMID 34386419, 2021). "As indicated by the qRT-PCR and West blot analysis, the mRNA expression level of MUC1 was significantly higher in tumor tissues compared with the adjacent tissues." (PMID 34729096, 2021). "Muc1 is a cell surface glycoprotein that is abundantly expressed in cancer cells, and it has been shown to be involved in tumor metastasis and promotion." (PMID 33985581, 2021). "Thus, in addition to its influence on promoting tumour cell spreading by interaction with tumour cell-associated MUC1, circulating PNA might also influence metastasis by enhancing the secretion of metastasis-promoting MCP-1 and IL-6 from the vascular endothelium." (PMID 34223877, 2021). "For example, miR-29a showed a tumor-suppressive role that involved targeting of MUC1, an oncogenic mucin that is overexpressed in PDAC and other epithelial cancers." (PMID 34440625, 2021). "They showed that VEGF is a downstream component of the MUC1/IGF-1R/AKT cascade and its activation plays an important role in tumor angiogenesis associated with MUC1." (PMID 33836774, 2021). "In this review, we aim to highlight the main molecular and cellular aspects of angiogenic possess in relation to the aberrant activation of MUC1 oncoprotein in tumor growth and metastasis." (PMID 33836774, 2021). "MTT assay results indicated that coculturingof T47D (a MUC1-positive tumour cell line)with anti-MUC1 redirected T cells led to a viabilityrate of 24.9 ± 9.19%, while T47D cell viability was85.01 ± 3.18% upon co-culture with untransducedT cells." (PMID 32347044, 2021). "Researchers have combined a vaccine consisting of the MUC1 core peptide with indomethacin to stimulate tumor-specific immune responses and alleviate the immunosuppressive microenvironment within breast tumors." (PMID 34207342, 2021). "At the same time, there were fewer reports regarding the downstream targets of tumor derived factors such as MUC1 that contains binding sites for NF-κβ in its promoter and that depends on STAT factors for its expression." (PMID 34070449, 2021). "Data clearly demonstrates that elimination of MUC1 in the host leads to the generation of immature immunosuppressive MDSCs which potentiates tumor growth." (PMID 34070449, 2021). "Further cell cycle analysis showed that knocking down MUC1 expression in HCCC9810 cells significantly reduced the ratio of tumor cells in S phase." (PMID 34729096, 2021). "Our finding of MUC1 expression in patient CSF is consistent with prior reports of using MUC1 to identify NSCLC circulating tumor cells." (PMID 34625644, 2021). "Two animal models demonstrated that YBX1 and MUC1 were key genes for tumor growth, and blood metastasis in vivo." (PMID 34976785, 2021). "This study set out to engineer anti-MUC1-CAR T cells and examine their anti-tumor effects against MUC1-expressing CCA cells." (PMID 33737613, 2021). "In line with results obtained with other antibodies, defucosylation of anti-MUC1 antibodies further enhanced anti-tumor responses." (PMID 34070311, 2021). "We observed that binding of MUC1 epitopes and direct cytotoxic effects on the tumor cells were both dose-dependent." (PMID 34070311, 2021). "MUC1 is undeniably an oncogene that transforms inflammation into cancer, enhances drug resistance, promotes tumor metastasis, and has been shown to play a significant role in cancer progression." (PMID 34207342, 2021). "TAAs are a type of antigens that derive from self-antigens but are selectively or over-expressed in tumor cells or involved in tissue differentiation such as MUC1." (PMID 34681560, 2021).
tumor (continued). "In the primary tumor cell line model, H295R, as well as in the metastatic cell line, MUC-1, RGZ (20 and 50 μM) dose-dependently reduced the cell number, whereas the effect was time-dependent only in the H295R cells." (PMID 34834449, 2021). "2μm HP SiPs functionalized with an IgG1 antibody to MUC1 (214D4), administered to human-MUC1 expressing mice (MUC1+) via the rectum, were detected at the location of the tumor." (PMID 34290978, 2021). "Mucin 1 (MUC1) is a membrane-tethered glycoprotein, which expresses on glandular epithelia and epithelial tumors, but tumor MUC1 differs from normal MUC1 by modified glycan side chains." (PMID 34572503, 2021). "This behavior of TA-MUC1 aids adherence of MUC1-expressing circulating tumor cells (CTCs) to a simulated blood vessel wall, then disseminating at distant sites to initiate secondary tumor formation." (PMID 33836774, 2021). "One example is PANVAC (pancreatic vaccine), a recombinant poxvirus-vector therapeutic vaccine that stimulates immune responses against the tumor antigens (carcinoembryonic antigen and MUC1)." (PMID 33724757, 2021). "Another example of a differentially glycosylated tumor antigen is the large mucin protein mucin 1 (MUC1), which is heavily O-glycosylated and often expresses truncated O-glycans, such as Tn antigen, in tumor cells." (PMID 34943864, 2021). "MUC1 isoforms such as MUC1/Y, which lacks the entire variable number of tandem repeat region, are involved in oncogenic processes by enhancing tumour initiation." (PMID 34452200, 2021). "Targeting the tumor MUC1 is therefore an essential mechanism to increase immunogenicity of the tumor." (PMID 34070449, 2021). "Subsequently, we described the in vitro functional activity ofVHH-based anti-MUC1 CAR-T cells by cytolysis of MUC1-positive tumour cells and cytokineproduction." (PMID 32347044, 2021). "Interaction of TF/MUC1 with galectin-3 also enhances tumor cell–endothelial heterotypic adhesion in circulating tumor cell extravasation." (PMID 34944925, 2021). "HMFG2 and SM3 were demonstrated to be effective against MUC1-expressing tumor cell lines in mouse models, both as antibodies and as scFv in the context of a CAR-T." (PMID 34070311, 2021). "The MUC1 vaccine has been tested in combination with other drugs to increase its anti-tumor effects." (PMID 34207342, 2021). "The results showed that while YBX1 silencing reduced tumor growth, MUC1 overexpression significantly promoted tumor growth." (PMID 34976785, 2021). "Cells from the primary tumor and metastasis display differences in the levels of the cognate receptors, as the H295R cells express both receptors, while the MUC-1 ones only CXCR4 at a significantly higher level than in the other cell model." (PMID 34834449, 2021). "To further explore the potential mechanism of MUC1 in promoting tumor progression, we used RNA-seq assay to identify the transcription differences of 10 pairs of ICC patients' tumor tissues and adjacent tissues." (PMID 34729096, 2021). "Our data showed that MUC1 was an independent predictor for overall survival and relapse-free survival after tumor resection." (PMID 34729096, 2021). "The expression of MUC1 can disrupt cell–cell and cell–matrix adhesions, and promote tumor adhesion and presumably metastasis." (PMID 33718143, 2021). "MUC1 antigen expression on tumor cells is known to be dynamic, due to the internalization of the protein through clathrin- and dynamic-mediated endocytosis." (PMID 34070311, 2021). "Our present study highlights their potential in the treatment of MUC1/Y-expressing tumours, as well as unveils the role of MUC1/Y in cancer growth and its potential as a target for cancer therapy." (PMID 34452200, 2021). "In contrast, differentiation-associated antigens, such as carcinoembryonic antigen (CEA) and Mucin 1 (MUC-1), are present in both tumor and normal cells but have a higher expression in cancer cells." (PMID 34199248, 2021).